C1QB (complement C1q B chain)
Diseases named in the same sentence as C1QB in open-access papers (continued):
Sharing a sentence is not in itself a finding about the gene and the disease.
gastric cancer (6 papers, 2020 to 2025). A primary or metastatic malignant neoplasm involving the stomach. "For instance, upregulation of C1QB at the mRNA level was reported in gastric cancer and head and neck squamous cell carcinoma, but C1QB mRNA was downregulated in esophageal squamous cell carcinoma." (PMID 36313902, 2022). "Based on these results, we further identified TYROBP and C1QB as the two key genes with prognostic value in gastric cancer." (PMID 33014868, 2020). "However, a different study revealed that gastric cancer patients with high C1QB expression had a poor prognosis." (PMID 36313902, 2022). "Overexpression of the C1QB gene at the mRNA level has also been shown in gastric cancer." (PMID 36313902, 2022). "CD14 and C1QB were identified using the GO and KEGG analysis, and we further conducted prognosis analyses of these two genes in intestinal-type gastric cancer, as HPAG usually progresses into intestinal-type gastric cancer." (PMID 40092684, 2025).
ovarian carcinoma (6 papers, 2020 to 2024). A malignant neoplasm originating from the surface ovarian epithelium. "By PPI network and MCODE module, TYROBP, ITGB2, C1QB, C1QA, CD53 and CD163 have top connectivity among all DEGs and are considered to have important relationship to immune response in ovarian cancer." (PMID 33987033, 2021). "TYROBP, ITGB2, C1QB, C1QA and CD53 in module B have the top connectivity among all DEGs and are considered to have important relationship to immune response in ovarian cancer." (PMID 33987033, 2021). "One study reported that C1QB could upregulate the expression of Fas and TNF-α and induce apoptosis of ovarian cancer cells, either independently or through a caspase cascade reaction." (PMID 36313902, 2022).
Cognitive impairment (5 papers, 2011 to 2025). Abnormal cognition is characterized by deficits in thinking, reasoning, or remembering. "A large number of patients surviving sepsis exhibit mental and cognitive impairment, and C1q pathways (C1qb, C1qc, and Tyrobp) are associated with the mental and cognitive impairment observed in the post-sepsis syndrome." (PMID 40426888, 2025). "In addition, recent studies showing alterations in expression of C1QB gene in hippocampus and cerebral cortex in the animal models of Alzheimer's disease, having some clinical features shared with schizophrenia such as neuron loss and cognitive impairment." (PMID 21951915, 2011). "Furthermore, carriers in the moderate cognitive impairment stage showed lower levels than controls of complement C1q subcomponent subunit-B [C1QB] and CD59, which was also observed in the replication cohort." (PMID 32460813, 2020).
pancreatic cancer (5 papers, 2010 to 2025). "C1QB can mediate growth factor-induced cancer cell chemotaxis and distant metastasis, including to the liver, which is a significant event in the progression of pancreatic cancer and is associated with an extremely poor prognosis." (PMID 37628784, 2023). "We visualized changes by UMAP, and found that C1qa, C1qb, and C1qc, immunosuppressive macrophage markers in pancreatic cancer, were upregulated in the ON compared with the OFF group." (PMID 39782689, 2025). "This study uses biomaterial scaffolds to identify a macrophage gene signature defined by high expression of C1qa, C1qb, and Trem2 that is elevated systemically in mouse and human pancreatic cancer." (PMID 33782087, 2021). "Compared with macrophages in normal tissue, pancreatic cancer patients exhibited high expression of C1QB in TAMs and peripheral blood, indicating that it may be a suitable liquid biopsy biomarker to predict prognosis." (PMID 36969247, 2023). "While C1qa, C1qb, and Trem2 are known drivers of alternatively activated macrophage polarization in a LPS-induced inflammation model, little is known about their involvement in pancreatic cancer." (PMID 33782087, 2021). "Moreover, C1QB levels in pancreatic cancer may serve as a predictor of disease given its role in the regulation of IGF-1/IGF-1R signaling, which plays a role in the cell spreading, and in the induction of hepatic metastasis." (PMID 37628784, 2023). "Finally, we determined that C1QA and C1QB expression is enriched in pancreatic cancer patient blood compared with healthy individuals, suggesting that the elevation of these markers may serve as a novel predictor of disease in PDA patients." (PMID 33782087, 2021). "Paralleling the mouse data, C1QA, C1QB, and TREM2 were up-regulated in macrophages from human pancreatic cancer compared with macrophages from the non-malignant pancreas." (PMID 33782087, 2021).
prion disease (5 papers, 2019 to 2024). A transmissible disease that is caused by a protein that is able to induce abnormal folding of normal cellular proteins, leading to characteristic spongiform brain changes, which are associated with neuronal loss without an inflammatory response. "The genes C1QB, C1QC, C7, and NCAM1 were downregulated for Ca and partake in the prion disease pathway." (PMID 31481722, 2019). "Five genes from the HIP negative correlates associated with the Prion disease pathway:C1QA,C7,C1QB,C6 andC1QC; these are all related to the complement pathway of the innate immune system." (PMID 31448102, 2019).
skin cutaneous melanoma (5 papers, 2019 to 2024). "In this study, survival analysis showed higher expression level of HLA class II co-expressed genes, especially APOL3, CD74, C1QA and C1QB, were associated with better prognosis in cutaneous melanoma." (PMID 31212865, 2019). "Recent studies have confirmed that C1QB is a reliable biomarker for identifying patients with early cutaneous melanoma and observing treatment outcomes in follow-up patients." (PMID 36110204, 2022). "Based on these data, we inferred that the relationship between central genes may contribute to C1QA, C1QB, and C1QC, thus prolonging survival in patients with cutaneous melanoma." (PMID 36110204, 2022). "However, the effect of C1QA, C1QB, and C1QC expression on tumour immunity and prognosis of cutaneous melanoma remains unclear." (PMID 36110204, 2022).
diabetes (4 papers, 2013 to 2025). "Additionally, C1qb has been identified as a candidate gene for diabetes susceptibility located on mouse chromosome 4." (PMID 40941112, 2025). "The complement factors (C1qb, C1qa, Cfh) are also involved in the complement activation classical pathway, but have not changed expression levels due to diabetes in previous studies." (PMID 24199937, 2013).
lung fibrosis (4 papers, 2017 to 2024). "C1qa, Fcgr1, C1qb, C1qc, Ccr5, Slc11a1, Aif1, Emr1 and Cxcl10 were identified as the most closely connected module which were highlighted in yellow, including 9 nodes and 32 edges, and the genes in this region were upregulated in pulmonary fibrosis." (PMID 35078421, 2022).
malaria (4 papers, 2016 to 2025). Malaria is a serious and sometimes fatal disease caused by a parasite that commonly infects a certain type of mosquito which feeds on humans. "The gene Cfp displayed a very similar expression pattern as C1qa, C1qb, and C1qc in response to blood-stage malaria, with a faster increase towards day 4 p.i. after an initial faster decrease on day 1 p.i. in vaccinated mice than in unvaccinated mice." (PMID 40243929, 2025). "Differentially expressed probes form these canonical pathways that were previously shown to play a role in severe malaria pathogenesis were TLR2, TLR4, TLR8, HSPA6, CR1, C1qA, C1qB, C1qC, FOS, and GZMB." (PMID 26961973, 2016). "Notably, complement genes (C1QA, C1QB, C1QC), apoptotic genes (PDL1, PDL2, APOL1, APOL2, FAS), inflammatory caspases (CASP1, CASP5), TLR pathway genes (TLR1, TLR4, TLR5, TLR8), cytokines (IL6, IL10), and granzyme (GZMB) were among the genes upregulated during symptomatic malaria." (PMID 39161730, 2024).
renal cell carcinoma (4 papers, 2020 to 2024). "According to Yamada's report 44, high expressed C1QB was significantly related to poor prognosis in renal cell carcinoma." (PMID 38817876, 2024). "The expression of C1QB is correlated with the stage of renal cell carcinoma and poor prognosis of patients." (PMID 34915882, 2021). "In renal cell carcinoma (RCC), C1QB expression can influence CSF-1-induced macrophage migration and hamper their adhesion and chemotaxis." (PMID 36969247, 2023).
Sepsis (4 papers, 2019 to 2025). Sepsis is defined as life-threatening organ dysfunction caused by a dysregulated host response to infection. "Among the top 40 DEGs analyzed by RNA sequencing of whole hippocampus tissue at day 3 following sepsis induction, we observed up-regulation of C1qa, C1qb, and C1qc encoding for complement factor C1q." (PMID 37235660, 2023).
staphylococcus aureus infection (4 papers, 2020 to 2023). An infectious process in which the bacteria Staphylococcus aureus is present. "The genes C1QA, C1QB, C1QC, C1S, C3, and C4A in cluster 2 were predominantly enriched in top ten pathways including Staphylococcus aureus infection, pertussis and complement and coagulation cascades." (PMID 37409113, 2023). "C1Q3, C1QB, and C1QA were enriched in both the staphylococcus aureus infection, complement, and coagulation cascades pathway." (PMID 33344459, 2020).
Stroke (4 papers, 2019 to 2025). Sudden impairment of blood flow to a part of the brain due to occlusion or rupture of an artery to the brain. "In MS and stroke, equal percentages of microglia nodules expressed C1qB (MS: 63 of 163 nodules, per donor 36.6% ± 6.0%, stroke: 22 of 68 nodules, per donor 30.5% ± 19.0%, p = 0.25)." (PMID 38396116, 2024). "At 8 weeks post-stroke, the top 10 genes were Cd44 (degree = 14), Fcgr2b (degree = 13), C1qb (degree = 13), Cd74 (degree = 12), C1qc (degree = 11), Cd14 (degree = 10), C4a (degree = 10), Spp1 (degree = 10), RT1-A2 (degree = 9), and Itgb2 (degree = 9)." (PMID 31888302, 2019). "Therefore, we stained the microglia nodules in MS and in stroke for complement components C1qB, C3d, and the membrane attack complex (MAC)." (PMID 38396116, 2024). "Microglia nodules compared to non-nodular (NA)WM in MS and in stroke shared only few communally upregulated DE genes (C1qB, RPGR, and SLC11A1), which are associated with involvement in activation of the classical complement pathway and in phagocytosis." (PMID 38396116, 2024). "The classical pathway, initiated by C1q‐a protein composed of C1QA, C1QB, and C1QC subunits, is a major contributor to stroke‐induced inflammation and vascular injury." (PMID 40842166, 2025). "C1qB was also upregulated by microglia nodules in stroke compared to stroke non-nodular WM, also after correction." (PMID 38396116, 2024). "At 4 weeks post-stroke, the top 10 gene products in the PPI network were Cd44 (degree = 17), C1qb (degree = 15), Fcgr2b (degree = 14), Spp1 (degree = 12), Cd74 (degree = 12), C4a (degree = 12), C1qa (degree = 12), C3 (degree = 10), Cd14 (degree = 10), and Itgb2 (degree = 10)." (PMID 31888302, 2019). "After correction, C1qB remained significantly differentially expressed for both comparisons, while SLC11A1 was only significantly upregulated by microglia nodules in stroke compared to stroke non-nodular WM." (PMID 38396116, 2024).
Alzheimer disease (3 papers, 2011 to 2022). A progressive, neurodegenerative disease characterized by loss of function and death of nerve cells in several areas of the brain leading to loss of cognitive function such as memory and language. "Finally, we successfully verified significantly lower levels (p<0.05) of eight proteins (A2GL, APOM, C1QB, C1QC, C1S, FBLN3, PTPRZ, and SEZ6) in Alzheimer’s disease compared to controls using an antibody-based detection method." (PMID 26950848, 2016).
cervical cancer (3 papers, 2022 to 2024). A primary or metastatic malignant neoplasm involving the cervix. "In addition, we identified the underlying function of C1QB in cervical cancer using GSEA." (PMID 36313902, 2022). "A combined SMD of 0.65 (95% CI: [0.52, 0.79], p < 0.001) revealed upregulation of C1QB mRNA in cervical cancer." (PMID 36313902, 2022). "We confirmed the overexpression of C1QB in cervical cancer at both mRNA and protein levels for the first time." (PMID 36313902, 2022). "The aim of this study is to demonstrate the expression and clinicopathological significance of complement C1q B chain (C1QB) in cervical cancer." (PMID 36313902, 2022). "We conducted an integrated analysis of C1QB mRNA expression in cervical cancer using public microarrays and RNA-seq data sets by calculating standard mean differences (SMDs)." (PMID 36313902, 2022). "The aim of the present study was to use immunohistochemical (IHC) staining to examine the expression status of the C1QB protein in cervical cancer tissues." (PMID 36313902, 2022). "The expression of C1QB protein was higher in cervical cancer samples than that in benign cervical tissue, LSIL, and HSIL samples (p < 0.05)." (PMID 36313902, 2022). "Collectively, the data presented here provide the first verification of the overexpression of C1QB in cervical cancer at both the mRNA and protein levels in 1,341 samples." (PMID 36313902, 2022). "In brief, we have demonstrated the overexpression of C1QB mRNA and protein in cervical cancer in both clinical specimens and multicenter samples." (PMID 36313902, 2022). "We also found that C1QB protein expression was positively correlated with P16 and Ki-67 expression in cervical cancer (p < 0.05)." (PMID 36313902, 2022). "This study confirmed the high expression of C1QB protein in clinicopathological specimens of cervical cancer." (PMID 36313902, 2022). "The positive rate of C1QB protein expression in the cervical cancer group was 75.8%, which was higher than that in the LSIL group and in the benign cervical tissue group (p < 0.05)." (PMID 36313902, 2022). "C1QB may be involved in apoptosis, autophagy and drug sensitivity, suggesting it could be an oncogene in cervical cancer." (PMID 39400959, 2024). "In cervical cancer, the expression of C1QB protein is related to P16 expression." (PMID 39650066, 2024). "In addition, we used multicenter high-throughput data sets to determine the expression level of C1QB in cervical cancer tissues at the mRNA level." (PMID 36313902, 2022). "C1QB may serve as an oncogene in the tumorigenesis of cervical cancer, but this possibility requires further study." (PMID 36313902, 2022). "In our study, we demonstrated that C1QB expression in cervical cancer might be related to both apoptosis and autophagy, suggesting the possible participation of C1QB in cervical cancer tumorigenesis." (PMID 36313902, 2022). "Cervical cancer with deeper infiltration (depth ≥1/2 muscle layer, p = 0.019), lymphovascular invasion (p = 0.012), and perineural invasion (p = 0.018) tended to have positive C1QB expression, and the difference was statistically significant." (PMID 36313902, 2022). "In our study, we demonstrated a positive correlation between C1QB expression and the expression of Ki-67 and P16 in cervical cancer, indicating that C1QB may act as a facilitating factor in cervical cancer tumorigenesis." (PMID 36313902, 2022). "C1QB expression may also be related to the depth of infiltration, lymphovascular invasion, and perineural invasion in cervical cancer (p < 0.05)." (PMID 36313902, 2022).
cervical cancer (continued). "In the present study, we found that positive C1QB expression was related to deeper invasion, lymphovascular invasion, and perineural invasion of cervical cancer, providing the first evidence for clinicopathological implications of C1QB expression in cervical cancer." (PMID 36313902, 2022). "In fact, C1QB may be an oncogene in cervical cancer, but this needs further study." (PMID 36313902, 2022). "In total, 120 cervical cancer tissues, as well as 20 samples each of high-grade squamous intraepithelial lesions (HSILs), low-grade squamous intraepithelial lesions (LSILs), and benign cervical tissue, were collected to evaluate the expression of C1QB protein via immunohistochemical staining." (PMID 36313902, 2022). "We also confirmed the upregulation of C1QB in cervical cancer at the mRNA level through a comprehensive analysis based on a large sample size (n of cervical cancer = 825 and n of non-tumor = 366)." (PMID 36313902, 2022). "The current study is the first to report a higher expression of C1QB protein in cervical cancer tissues than in non-tumor cervical tissues (based on the PubMed database, as of December 28, 2021)." (PMID 36313902, 2022). "We explored the latent mechanisms of C1QB in cervical cancer by conducting GSEA, and we determined that C1QB may have a function related to apoptosis." (PMID 36313902, 2022). "However, dysregulation of C1QB has not yet been identified in cervical cancer." (PMID 36313902, 2022).
lupus erythematosus (3 papers, 2011 to 2020). An autoimmune, connective tissue chronic inflammatory disorder affecting the skin, joints, kidneys, lungs, heart, and the peripheral blood cells. "The functionality of C1QA rs292001 and C1QB rs631090 has been previously shown in lupus erythematosus." (PMID 21951915, 2011). "C1QB (complement C1q B chain) or C1QC (complement C1q C chain) encodes the C-chain or B-chain polypeptide of serum complement subcomponent C1q, respectively, and deficiency of C1q is associated with glomerulonephritis and lupus erythematosus." (PMID 32821283, 2020).
memory impairment (3 papers, 2020 to 2024). "All these results strongly implied that C1qb is a potential therapeutic target for post-ischemia memory impairment." (PMID 38180614, 2024).